STBD1 (starch binding domain 1)
Description:
Acts as a cargo receptor for glycogen. Delivers its cargo to an autophagic pathway called glycophagy, resulting in the transport of glycogen to lysosomes.
Synonyms: GENX-3414; FLJ41801; GENEX3414
Tractability: Antibody: UniProt places it where antibodies can reach, with high confidence; its Gene Ontology location is reachable by antibodies, with high confidence; UniProt predicts a signal peptide or a membrane-spanning region. PROTAC: UniProt records ubiquitination sites on it; its protein half-life has been measured.
Gene: Protein-coding gene on chromosome 4 (76,306,733 to 76,311,130, forward strand). Ensembl gene ENSG00000118804.
Subcellular location: Preautophagosomal structure membrane; Endoplasmic reticulum membrane; Cell membrane, sarcolemma, T-tubule
Subcellular location (Human Protein Atlas): Endoplasmic reticulum
Pathways (Reactome):
Signal Transduction: RAC2 GTPase cycle; RAC3 GTPase cycle; RHOA GTPase cycle; RHOD GTPase cycle; RHOG GTPase cycle
Immune System: Neutrophil degranulation
Gene Ontology:
Molecular function: enzyme binding; glycogen binding; polysaccharide binding; protein binding; cargo receptor activity; carbohydrate binding; starch binding
Biological process: glycogen catabolic process; glycophagy; lysosomal transport; substrate localization to autophagosome; vesicle-mediated transport
Cellular component: endoplasmic reticulum; endoplasmic reticulum membrane; membrane; perinuclear region of cytoplasm; phagophore assembly site membrane; plasma membrane; T-tubule; ficolin-1-rich granule membrane; tertiary granule membrane
Genetic constraint (gnomAD): Loss-of-function variants: 16 observed, 14.39 expected, observed/expected ratio (o/e) 1.11, 90% interval 0.75 to 1.67. The upper end of that interval is the gene's LOEUF score, 1.67, which puts it in group 6 of 6, group 1 being the genes least tolerant of losing a copy. Missense variants: 427 observed, 457.96 expected, observed/expected ratio (o/e) 0.93, 90% interval 0.86 to 1.01. Synonymous variants: 146 observed, 170.24 expected, observed/expected ratio (o/e) 0.86, 90% interval 0.75 to 0.98.
Homologues: Orthologues: chimpanzee STBD1 (98% identical), dog STBD1 (66% identical), mouse Stbd1 (63% identical), rat Stbd1 (63% identical), rabbit STBD1 (57% identical), guinea pig STBD1 (54% identical), tropical clawed frog stbd1 (31% identical), zebrafish stbd1 (22% identical).
Diseases named in the same sentence as STBD1 in open-access papers:
STBD1 is named in the same sentence as 15 diseases in open-access papers, as found by Europe PMC text mining. Sharing a sentence is not in itself a finding about the gene and the disease. The quoted sentences say what the papers report.
colon cancer (1 paper, 2021). "To investigate whether the expression of STBD1 is altered in tumor samples, we performed immunohistochemistry (IHC) staining to examine 27 colon cancer specimens and paired adjacent noncancerous tissues." (PMID 34059679, 2021).
colorectal carcinoma (1 paper, 2021). A malignant epithelial neoplasm that arises from the colon or rectum and invades through the muscularis mucosa into the submucosa. "Mutation of STBD1 (W203C) is found in patients with intestinal adenocarcinoma, and we also examined colorectal carcinoma cell line HCT116." (PMID 34059679, 2021).
gastric cancer (1 paper, 2021). A primary or metastatic malignant neoplasm involving the stomach. "To determine whether STBD1 plays a similar role in other types of cancer cells, we survey the expression of STBD1 in different cell lines and find that gastric cancer cell line HGC27 has the lowest expression." (PMID 34059679, 2021).
hepatoma (1 paper, 2014). "In HepG2 hepatoma cells, overexpressed STBD1 could associate with endogenous GS." (PMID 24837458, 2014).
lung carcinoma (1 paper, 2021). "Similar to our results from lung cancer cell lines, over-expression of STBD1 WT, but not STBD1 W203C, in HGC27 cells, reduces the cell proliferation rate." (PMID 34059679, 2021).
cancer (3 papers, 2021 to 2024). A tumor composed of atypical neoplastic, often pleomorphic cells that invade other tissues. "Our data are consistent with the observation that the expression of STBD1 is significantly downregulated in a diverse array of human tumors, and that the expression level of STBD1 is associated with cancer patients’ survival probability." (PMID 34059679, 2021). "Taken together, our results suggest that STBD1 suppresses tumor growth by inhibiting multiple cancer hallmark traits." (PMID 34059679, 2021). "Suppression of STBD1—either via knockdown or expression of the mutant—also promotes the expression of multiple cancer hallmark genes, including c-Myc, NFKB1, and AKT1, although the exact underlying mechanisms remain to be determined." (PMID 34059679, 2021). "In particular, we observe STBD1, a protein involved in glycophagy, to be potentially associated with human cancer." (PMID 34059679, 2021). "However, evidence supports a role for glycophagy in cancer as a mutation of the STBD1 which induces lysosomal glycogen accumulation in cancer cells." (PMID 39479019, 2024). "Altogether, we discover that STBD1 has putative tumor-suppressive functions, and our findings indicate that mutation or lower expression of STBD1 may promote cancer growth in patients." (PMID 34059679, 2021). "At the pan-cancer level, it is found that a higher mRNA expression level or a lower DNA methylation level of STBD1 is significantly associated with a higher survival probability, indicating STBD1 might, in general, have tumor-suppressive functions." (PMID 34059679, 2021). "KEGG-based enrichment analysis indicates that these differentially expressed genes (DEGs) are enriched in cancer-related pathways, such as transcriptional misregulation and microRNAs in cancer, indicating a potential role of STBD1 in cancer development." (PMID 34059679, 2021). "Depletion of STBD1 or disruption of its association with LC3 leads to enhancement of glycolysis and likely the pentose phosphate pathway in cancer cells, and promotes cancer growth." (PMID 34059679, 2021). "From the network, it can be found how LIRCPs affect human cancer through the nine functional aspects, and highlight the functional importance of STBD1 in inhibiting cancer growth through modulating glycophagy." (PMID 34059679, 2021). "Overall, our data suggest that STBD1 inhibits cancer growth, likely through altering gene transcription and rewiring the glycolysis/gluconeogenesis pathway." (PMID 34059679, 2021). "Taken together, depletion of STBD1 leads to substantial reprogramming of glucose metabolism in cancer cells through enhanced glycolysis." (PMID 34059679, 2021). "We show that STBD1 suppression promotes cancer cell proliferation, detected by the MTT assay and the proliferation marker Ki67." (PMID 34059679, 2021). "Mechanistically, STBD1 inhibits tumor growth via metabolic reprogramming in cancer cells, including rewiring glycolysis and the pentose phosphate pathway." (PMID 34059679, 2021). "Although we focus on testing the role of STBD1-mediated autophagy in cancer in this study, our rich dataset opens up the discovery of other uncharted autophagy pathways that regulate the development of cancer." (PMID 34059679, 2021). "The expression of STBD1 at the protein level is significantly lower in the cancer tissues in comparison with that in the adjacent non-carcinoma tissues (~56% of paracancer)." (PMID 34059679, 2021). "As deletion of STBD1 can enhance glycolysis in cancer cells, we speculate that shSTBD1 HCT116 is more dependent on exogenous glucose." (PMID 34059679, 2021). "Since shSTBD1 HCT116 cells are more dependent on glycolysis than shControl cells, depletion of STBD1 may sensitize cancer cells to glycolysis inhibition." (PMID 34059679, 2021). "To test whether STBD1 inhibits cancer growth in vivo, we establish a tumor xenograft model through subcutaneous injecting HCT116 cells into immunodeficient mice." (PMID 34059679, 2021).
cancer (continued). "To further confirm our observations, we test how the depletion of STBD1 affects cancer growth." (PMID 34059679, 2021). "Thus, STBD1 inhibits cell proliferation in multiple types of cancer cells." (PMID 34059679, 2021). "They further examined STBD1, a glycogen autophagy receptor, and found that it inhibits tumor growth and that the cancer-associated LAM inhibits its interaction with LC3 and abolishes its cancer-suppressing capability, drawing a connection between glycogen autophagy and tumor suppression." (PMID 34829881, 2021). "Using a combination of transcriptomic, metabolomic and additional experimental assays, we show that STBD1, a poorly-characterized protein, inhibits tumor growth via modulating glycogen autophagy, while a patient-derived W203C mutation on LIR abolishes its cancer inhibitory function." (PMID 34059679, 2021). "The discovery that 2-DG, a glycolysis inhibitor, significantly inhibits the growth of STBD1 low-expressing cancer cells, indicates that targeting glycolysis could represent an effective personalized targeting strategy for the patients with STBD1 low-expressing tumors." (PMID 34059679, 2021). "Among these candidate genes, we functionally confirm that starch-binding domain-containing protein 1 (STBD1), a gene involved in transporting glycogen to lysosomes, has a previously unappreciated role in suppressing cancer growth." (PMID 34059679, 2021). "Thus, STBD1 might have different roles in distinct types of cancer." (PMID 34059679, 2021).
tumor (3 papers, 2021 to 2026). "We use a combination of transcriptomics, metabolomics and additional experimental assays to study the role of STBD1 in tumor proliferation and the underlying mechanism." (PMID 34059679, 2021). "Depletion of STBD1 results in enhanced tumor growth in mice (the weight of tumor: shControl = 0.44 ± 0.08; shSTBD1 = 0.7539 ± 0.10)." (PMID 34059679, 2021). "To understand how STBD1 inhibits tumor growth, we compare the gene expression profiles of shControl and shSTBD1 HCT116 cells using RNA-seq." (PMID 34059679, 2021). "Taken together, our results indicate that STBD1 has potential tumor-suppressive activity through interacting with LC3B and participating in glycophagy." (PMID 34059679, 2021). "The dysfunction of the glycogen-specific autophagy receptor STBD1 leads to glycogen accumulation and inhibition of glycophagy, which has been proven to promote metabolic reprogramming and tumor growth, suggesting that the impairment of glycophagy is closely related to tumor occurrence." (PMID 41522193, 2026). "Furthermore, shSTBD1/WT markedly suppresses tumor growth in the xenograft model, in comparison with control (plvx neo) and shSTBD1/W203C (the weight of tumor: plvx neo = 0.704 ± 0.181; STBD1 WT = 0.269 ± 0.145; STBD1 W203C = 0.515 ± 0.244)." (PMID 34059679, 2021). "To further determine whether STBD1 regulates tumor growth via a role in glycophagy, we test another mediator of glycophagy, lysosomal acid α-acid glycosidase (GAA)." (PMID 34059679, 2021). "Similarly, STBD1 is significantly downregulated in cancers such as colon cancer, which directly impairs the targeting of glycogen to autophagosomes and may promote the growth and metabolic adaptation of tumor cells." (PMID 41522193, 2026). "By demonstrating that STBD1 and GAA have potential tumor-suppressive functions, we identify the previously uncharacterized connection between glycophagy and tumorigenesis." (PMID 34059679, 2021).
kidney diseases (1 paper, 2024). "STBD1 is identified in a GWAS meta-analysis that prioritized target genes for kidney diseases." (PMID 38279093, 2024).
STBD1 also shares sentences with these, for which no sentence is quoted: COVID-19 (1 paper); diabetic kidney disease (1); glioma (1); infection (1); ischemia (1); Pompe disease (1); preeclampsia (1).